INS (insulin)
Diseases named in the same sentence as INS in open-access papers (continued):
Sharing a sentence is not in itself a finding about the gene and the disease.
Insulin resistance (continued). "In animal studies, resistin functions to inhibit insulin signaling and glucose uptake, thus causing insulin resistance." (PMID 38473112, 2024). "Insulin resistance is believed to play a role in the pathogenesis of EC, with elevated insulin levels being associated with both EC and lymph node metastasis, indicating a poorer prognosis." (PMID 38543097, 2024). "In the heart, insulin resistance has been viewed primarily from the perspective of defective glucose metabolism caused by diminished insulin-stimulated glucose uptake." (PMID 38796064, 2024). "Early-onset T2DM is strongly associated with obesity, metabolic syndrome features, insulin resistance, family history, and necessitates faster progression to insulin therapy, i.e., in 2–5 years after diagnosis in >50% of patients." (PMID 38472622, 2024). "Plasma clusterin has been associated with diabetes mellitus, while polymorphisms of the CLU gene, the gene encoding clusterin, are linked to impaired insulin secretion and insulin resistance." (PMID 38396489, 2024). "Type 2 diabetes (T2D) is a chronic metabolic disease characterized by insulin resistance, deficient insulin secretion, and hyperglycemia, which results in long-term complications." (PMID 38182717, 2024). "Previous studies have indicated that the systemic influence of hyperglycemia induces insulin resistance, which impairs insulin signaling in the brain and causes cognitive decline." (PMID 38664771, 2024). "Insulin resistance (IR) is a state of reduced sensitivity and responsiveness to the action of insulin and has been shown to be a hallmark of proceeding diabetes and CV diseases (CVDs)." (PMID 38184591, 2024). "Increased fecal propionate has been associated with increased risk of type 2 diabetes, and supplementation with propionate has been found to increase plasma levels of glucagon and insulin, increasing the risk of insulin resistance and weight gain." (PMID 38262952, 2024). "Research on humans has shown that consuming caffeoylquinic acid-rich extracts over the long term lowers blood glucose levels, increases insulin response, alleviates hepatic insulin resistance, lowers serum lipids, and facilitates weight loss." (PMID 38611548, 2024). "A progressive insulin production deficiency, often known as insulin resistance (IR), and an insensitive bodily reaction to insulin cause type 2 diabetes." (PMID 38311623, 2024). "In contrast, type 2 diabetes is attributed to insulin resistance and inadequate insulin secretion, closely linked to obesity, unhealthy lifestyles, and genetic factors." (PMID 38780218, 2024). "Another contributing factor is insulin resistance, which is often associated with hyperinsulinemia—a condition where the body compensates for impaired insulin function by producing excess insulin." (PMID 39518104, 2024). "Large adipocytes release pro-inflammatory cytokines, which can promote glucose intolerance, insulin resistance, and type 2 diabetes, whereas small adipocytes tend to be associated with improved glucose regulation and increased insulin sensitivity." (PMID 39519233, 2024). "The cause of PCOS is not completely clear; however, the most common causes are genetic predisposition, increased insulin secretion, insulin resistance, obesity, and environmental and chemical contamination." (PMID 38737668, 2024). "Although increased insulin resistance and inadequate compensation for the body's insulin needs are well established to be associated with GDM, the detailed mechanism has not been fully characterized." (PMID 38429982, 2024). "Many in-vivo studies and models of diet-induced insulin resistance have linked decreased tissue insulin sensitivity with factors such as lipid accumulation, endoplasmic-reticulum stress, and inflammatory stress responses." (PMID 39033139, 2024). "Impaired cognitive function is associated with insulin resistance, as neuronal metabolism and synaptic efficacy suffer from the desensitization of insulin signaling pathways." (PMID 38921025, 2024).
Insulin resistance (continued). "Insulin resistance caused by lipids in skeletal muscle, observed as a defect in the uptake of glucose, is due to limited utilization of glucose, stimulated by insulin." (PMID 38397072, 2024). "Obesity-associated insulin resistance leads to decreased adiponectin levels, elevated insulin, and bio-available IGF-I levels." (PMID 38339282, 2024). "Alternatively, enhanced lipogenic capacity (i.e., lipid storage capacity) in adipose tissue prevents systemic insulin resistance in mouse models of obesity and is associated with increased insulin sensitivity in people." (PMID 39405118, 2024). "Abnormalities in the phosphorylation of AKT kinases are associated with the occurrence of insulin resistance in cells, and restoring their sensitivity to insulin is a key aspect of the pharmacotherapy of metabolic disorders." (PMID 38399444, 2024). "In T2D, as insulin demands increase in response to insulin resistance, β-cells undergo compensatory hyperplasia, ultimately causing β-cell exhaustion and death." (PMID 39022651, 2024). "Impaired insulin action not only causes insulin resistance but also promotes protein degradation and hampers protein synthesis in skeletal muscle cells, resulting in sarcopenia." (PMID 39361190, 2024). "In fact, improper ECM remodeling, even though incompletely understood, has been implicated in the development of insulin resistance by increasing the physical barrier to insulin transport or through integrin signaling." (PMID 37988600, 2024). "Insulin resistance secondary to pyometra was associated with higher basal serum insulin and higher area under the curve after an intravenous glucose load, as well as glucose intolerance during the IVGTT." (PMID 38539988, 2024). "In mice, conditional deletion of CEACAM1 in hepatocytes impairs insulin clearance to cause hyperinsulinemia-driven insulin resistance with steatohepatitis and hepatic fibrosis even when mice are fed a regular chow diet." (PMID 39640841, 2024). "Insulin resistance and sarcopenia share a close association, as insulin plays a crucial role in maintaining muscle protein synthesis and degradation balance." (PMID 39058051, 2024). "Total cholesterol, insulin, and insulin resistance were greater in carriers of one or two risk alleles than in wild-type carriers." (PMID 38674326, 2024). "Lower irisin levels in PWS compared with OC,Strong association between irisin with insulin resistance, C-peptide and insulin OGTT 120’ levels." (PMID 38737552, 2024). "The insulin-insulin receptor-insulin receptor substrate-1-PI3K pathway is strongly associated with insulin resistance." (PMID 38433280, 2024). "It is closely linked to insulin resistance, which hinders cells from responding effectively to insulin and leads to elevated blood glucose levels." (PMID 39310549, 2024). "Obesity and insulin resistance are known to contribute to this development, but beta cell and alpha cell functions, respectively, have been shown to alter insulin secretion and cause a hyperglucagonemic state in adults." (PMID 39459592, 2024). "Biologically, women benefit from the insulin-sensitizing effects of estrogen until menopause, whereas men tend to have higher levels of androgens and more visceral fat, both linked to increased insulin resistance." (PMID 39606490, 2024). "Second, ageing is associated with lower IGF-1 and increased insulin resistance, and exposure to air pollutants has shown to be a risk factor of insulin resistance and reduced insulin sensitivity over time." (PMID 38303067, 2024). "Around half of patients with hypertension experience insulin resistance, a disturbance in insulin metabolism increasingly linked to hypertension and related cardiovascular diseases." (PMID 39925628, 2024). "Long-term WD feeding increased mice body weight (BW), liver/BW ratio and body condition score (BCS), transaminases, glucose and insulin, and caused dyslipidemia and insulin resistance." (PMID 39330437, 2024).
Insulin resistance (continued). "Obesity is associated with high levels of insulin (hyperinsulinemia), which stems from insulin resistance caused by an increased cytokine release." (PMID 39728103, 2024). "As insulin resistance is caused by chronic high concentrations of insulin, intervention should focus on limiting postprandial insulin secretion." (PMID 38474713, 2024). "Elevated HOMA-IR values are associated with reduced insulin sensitivity, indicating insulin resistance." (PMID 39770882, 2024). "3–7% weight loss showed greater reduction in 2 h OGTT glucose/insulin and insulin resistance in men than in women; >7% weight loss showed greater reduction in 2 h OGTT and hemoglobin A1C in men compared with women." (PMID 39275236, 2024). "These two clusters are also most strongly associated with reduced insulin secretion and lower insulin resistance." (PMID 38374256, 2024). "The smaller volume of hippocampal tail was associated with higher plasma insulin and insulin resistance in FEPs, at the one-year follow-up." (PMID 39085221, 2024). "It is categorized into different types: type I diabetes, which is attributed to severely decreased insulin secretion, and type 2 diabetes, which is characterized by insulin resistance and deficient insulin secretion." (PMID 39583394, 2024). "The oxidative stress linked to hyperglycemia impairs insulin signaling and β-cell function, contributing to insulin resistance, a hallmark of T2DM." (PMID 39857603, 2024). "A major cause of childhood insulin resistance is a common pattern of lipid distribution characterized by increased lipid deposition in insulin-responsive tissues such as the liver, skeletal and visceral tissues." (PMID 38233797, 2024). "Skeletal muscle is the primary tissue responsible for insulin-dependent glucose uptake in vivo and skeletal muscle insulin resistance is a hallmark of type 2 diabetes." (PMID 39188637, 2024). "Increased insulin resistance and pancreatic β-cell apoptosis and decreased insulin signaling through estrogen receptor α (ER α) caused by decreased estrogen levels contribute to an increased risk of DM." (PMID 38745339, 2024). "In contrast to endothelial cells, its loss in hepatocytes also causes hepatic insulin resistance and steatosis, consistent with its role in promoting insulin clearance in these cells." (PMID 39640841, 2024). "Ectopic lipid accumulation in skeletal muscle is strongly associated with insulin resistance, as it disrupts insulin signaling pathways and impairs glucose uptake and utilization." (PMID 38920999, 2024). "Non-insulin-based insulin resistance (NI-IR) indices have been reported to have an association with prevalent hypertension, however, no cohort studies to date have compared their prediction of hypertension among young adults." (PMID 38664804, 2024). "The onset of inflammatory responses has also been shown to be intricately linked with the emergence of insulin resistance, with studies showing that insulin administration can have positive effects on memory and cognitive functions in animal models." (PMID 39769264, 2024). "In contrast, type 2 diabetes is primarily caused by insulin resistance coupled with reduced insulin output, affecting approximately 8.5% of the adult population." (PMID 39070316, 2024). "Activation of this pathway impairs insulin signaling and causes insulin resistance with impaired insulin-induced suppression of white adipose tissue lipolysis." (PMID 37934800, 2024). "HFHSD consumption is commonly associated with impaired insulin sensitivity and insulin resistance, particularly exacerbating metabolic syndrome in vulnerable individuals." (PMID 38257133, 2024). "Individuals with insulin resistance exhibit disrupted rhythmic patterns in the expression of muscle circadian clock-associated genes, suggesting that insulin signaling plays an important role in the circadian clock of muscles." (PMID 39165284, 2024).
Insulin resistance (continued). "Insulin resistance is a hallmark of this condition, where cells become less responsive to insulin, leading to elevated blood glucose levels." (PMID 39796335, 2024). "In this review, we attempted to explain how epigenetic modifications can impact the insulin levels in the periphery to cause peripheral insulin resistance." (PMID 38534427, 2024). "While insulin and IGF signaling are known for their broad impacts on metabolism and growth, genetic manipulation studies in insulin/IGF1 signaling shows that they cause insulin resistance and hyperglycemia, while extending longevity." (PMID 39161341, 2024). "This indicated that increased insulin sensitivity (decreased insulin resistance) was linearly associated with increased eGFR in SLE patients, and this association was independent of the IMAT area." (PMID 38886276, 2024). "Impaired insulin signaling in the brain, often referred to as brain insulin resistance, has been associated with cognitive decline and neurodegenerative diseases like Alzheimer’s disease." (PMID 39659426, 2024). "The present study provides evidence supporting the idea that hyperinsulinemic condition causes neuronal insulin resistance, as indicated by the downregulation of insulin signalling molecules, including PI3K/AKT, with the upregulation of GSK-3β and TTBK1." (PMID 38536493, 2024). "Insulin resistance is characterized by the loss of sensitivity to insulin within insulin-dependent tissues such as adipocytes, muscles and liver." (PMID 39635529, 2024). "Hepatic lipid accumulation is strongly associated with insulin resistance and type 2 diabetes, as it disrupts hepatic insulin signaling and promotes gluconeogenesis, leading to increased hepatic glucose production." (PMID 38920999, 2024). "On the other hand, low levels of adiponectin in circulation are linked to insulin resistance and obesity, which can alter glucose metabolism and insulin sensitivity." (PMID 38820505, 2024). "Insulin resistance, a hallmark of metabolic syndrome, leads to impaired glucose tolerance and increased insulin secretion by pancreatic beta cells." (PMID 39310549, 2024). "In subjects with NAFLD, it has been observed that hepatic steatosis is more closely linked to skeletal muscle‐induced insulin resistance than hepatic insulin resistance, supporting the critical role of skeletal muscle in the development of SLD." (PMID 39011807, 2024). "Both the fasting blood glucose and oral tolerance tests have been used as hallmark tests for the evaluation of insulin sensitivity and insulin resistance." (PMID 38416754, 2024). "The PI3K is a crucial protein in both adipogenesis and osteogenesis of mesenchymal stem cells and plays a central role in insulin signaling where the disruption of the PI3k/AKT signaling is associated with insulin resistance and obesity." (PMID 39705291, 2024). "Insulin resistance causes the body to require more insulin to maintain normal blood glucose levels, but the vasodilatory effect of insulin on blood vessels is diminished, potentially leading to increased blood pressure." (PMID 38689862, 2024). "Further, lower serum amylase was associated with decreased insulin levels and higher estimates of insulin resistance in middle‐aged adult humans." (PMID 38955666, 2024). "In pregnant women, metabolic parameters related to insulin levels and insulin resistance were significantly associated with core fucosylated, bisected (FA2B), and afucosylated, disialylated (A2G2S2), glycan structures." (PMID 39337475, 2024). "Insulin resistance is caused by a defect in insulin signaling that inhibits glucose uptake into target cells." (PMID 39599757, 2024). "Thyroid hormones, especially FT3 and FT4, can act as insulin agonists or antagonists in different organs, and several studies have confirmed that hypothyroidism is associated with the occurrence of insulin resistance." (PMID 39457682, 2024).
Insulin resistance (continued). "Among the underlying mechanisms, the hyperglycaemia-induced mitogenic pathways and the use of insulin analogues are added to hypercortisolism-associated insulin resistance." (PMID 39062179, 2024). "Increased levels of urea in the kidneys are associated with insulin resistance and suppression of insulin, with evidence from both experimental and epidemiological studies." (PMID 38730245, 2024). "A body weight reduction plan (reduced energy intake) resulted in significant weight loss in ponies with diagnosed insulin resistance, leading to improved insulin sensitivity." (PMID 38473112, 2024). "This then causes a reduced IRS-1-associated phosphatidyl inositol 3 kinase activity and thereby decreases insulin-stimulated glucose transport (Glut 4) activity (a hallmark of insulin resistance)." (PMID 38791525, 2024). "An increased liver fat content will cause relative (hepatic) insulin resistance, and this results in higher fasting glucose levels by decreasing the insulin-mediated suppression of hepatic glucose production." (PMID 38791525, 2024). "IL-1β can activate pro-inflammatory mediators and infiltrate macrophages, cause insulin resistance and oxidative stress, and lead to β cell dysfunction and impaired insulin secretion." (PMID 38254574, 2024). "In the onset of T2DM, pancreatic β-cells struggle to cope with the increased insulin demand caused by insulin resistance." (PMID 38951808, 2024). "The two main features of T2DM are insulin resistance in target tissues and a relative deficiency in insulin production by pancreatic β-cells, and the production of reactive oxygen species (ROS) is closely related to insulin resistance." (PMID 39229371, 2024). "As insulin resistance persists, more insulin is secreted to maintain normal blood glucose levels, causing hyperplasia and the dysfunction of pancreatic β cells." (PMID 39599757, 2024). "The pathogenesis of GDM is not fully known, but it is thought to be caused by impaired insulin production and insulin resistance induced by diabetogenic factors." (PMID 38930029, 2024). "The decrease in insulin secretion from pancreatic β-cells and acquired insulin resistance in adipose tissue, liver and muscle are the main causes of hyperglycaemia." (PMID 38164186, 2024). "Circulating palmitoleate strongly correlated with insulin sensitivity in subjects at increased risk for type 2 diabetes, suggesting a major role of palmitoleate in the pathogenesis of insulin resistance in humans." (PMID 39201497, 2024). "In obese individuals with insulin resistance, weight loss surgery leads to improved insulin sensitivity and adaptive growth of beta cells, potentially causing hypoglycemia." (PMID 38817472, 2024). "The interactions between AVP and insulin are significantly affected in hypertension, cardiac failure, obesity, insulin deficiency, and insulin resistance." (PMID 39769071, 2024). "Our data support the association of aging with glucose intolerance, insulin resistance, and impaired insulin secretion under hyperglycemic conditions, as evident in HOMA-IR and in vivo/ex vivo GSIS." (PMID 38794702, 2024). "There is an interaction between elevated FFA levels caused by obesity and decreases in glucose uptake and insulin secretion from β-cells, resulting in hyperglycemia and insulin resistance." (PMID 38892574, 2024). "In humans, weight loss, reductions in hepatic fat and hepatic insulin resistance and, consequently, reductions in circulating insulin are associated with increases in IGFBP-1, which we also observed in our study in patients with low IGFBP-1 levels at baseline." (PMID 38928106, 2024). "Among males and females, increased total fat mass, trunk fat mass, and BMI during growth from age 15 to 24 years were associated with increased fasting insulin concentration and insulin resistance but with decreased fasting glucose." (PMID 38173399, 2024).